CST3 (cystatin C)
Diseases named in the same sentence as CST3 in open-access papers (continued):
Sharing a sentence is not in itself a finding about the gene and the disease.
neurological disease (18 papers, 2010 to 2025). "Human cystatin C (hCC) is a small cysteine protease inhibitor whose oligomerization by propagated domain swapping is linked to certain neurological disorders." (PMID 27573935, 2016). "For patients with neurological diseases, it has been confirmed that level of cystatin C was positively related with severity and adverse outcome of acute ischemic stroke, aneurysmal subarachnoid hemorrhage." (PMID 33478333, 2021). "Beyond the role as a reliable marker for kidney function, cystatin C has also received much attention due to its multiple biological activities involved in neurological diseases." (PMID 29930507, 2018). "Once the concentration-to-activity relationship is clarified, it will be possible to draw conclusions about the potential effects of altered cystatin C concentration in neurological disease states." (PMID 23497730, 2013). "Changes in expression and secretion levels of cystatin C (CysC) in the brain in various neurological disorders and in animal models of neurodegeneration underscore a role for CysC in these conditions." (PMID 22783166, 2012). "In order to assess the diagnostic utility of cystatin C, we first compared the mean first-draw cystatin C levels among ALS patients, neurologic disease controls, and healthy controls." (PMID 21151566, 2010). "For instance, in OPC protein–protein interaction (PPI) network, proteins involved in Golgi vesicle transport (such as Vamp3, Golga7, Vti1b and Snx1), Cell redox homeostasis (such as Tnx2 and Gsr), nervous system disease (such as Got1, Gm2a, Apoe and Cst3) and other functions were identified." (PMID 32974003, 2020). "While the alteration of CSF cystatin C concentration in various neurological disorders has been established, the relationship between the concentration and functional activity of this protein within the CSF is unknown." (PMID 23497730, 2013). "We found that plasma cystatin C levels are equivalently elevated in both ALS patients and disease controls relative to healthy controls, indicating that elevated plasma cystatin C is a nonspecific finding associated with neurologic disease states." (PMID 21151566, 2010). "Therefore, cystatin C may have multiple functions relevant to the pathogenesis and progression of neurological disease." (PMID 23497730, 2013). "We used a papain inhibition assay to evaluate the total cystatin C activity in CSF samples from 23 ALS patients, 23 healthy controls, and 23 neurological disease controls." (PMID 23497730, 2013). "Prior studies using SELDI-TOF-MS found significantly lower cystatin C abundance in the CSF of ALS patients relative to healthy controls and mixed healthy/neurologic disease controls." (PMID 21151566, 2010). "Two prior surface-enhanced laser desorption/ionization time of flight mass spectrometry (SELDI-TOF-MS) studies reported significant decreases in CSF cystatin C levels in ALS patients relative to healthy controls and mixed healthy/neurologic disease controls." (PMID 21151566, 2010). "Our results also suggest that cystatin C is the major cysteine protease inhibitor in human CSF and altered CSF cystatin C concentration may play a role in the pathobiology of ALS and other neurological diseases." (PMID 23497730, 2013). "However, blood-borne levels of cystatin C have not been evaluated as a biomarker candidate for neurologic disorders." (PMID 21151566, 2010).
heart disease (14 papers, 2017 to 2026). "In both sexes, age, cystatin-C, and the presence of other heart disease were the only three predictor variables present in all five models." (PMID 41267842, 2025). "In general, age, cystatin-C, and presence of other heart disease, were the most consistently important predictor variables." (PMID 41267842, 2025). "Age, cystatin-C, lifetime treatments/medications, other heart disease, systolic blood pressure, and spirometry measures were identified as high-risk factors in both model types for both sexes." (PMID 41267842, 2025). "In this study, the analysis of average cystatin C concentration and the cystatin C/creatinine ratio revealed marginally higher values in dogs with heart disease compared to the control group." (PMID 38731309, 2024). "This study indicates that while cystatin C may be a useful biomarker for early renal damage in dogs with DCM, further research with larger groups and across different stages of heart disease is needed to confirm its diagnostic utility." (PMID 38731309, 2024). "Additionally, serum cystatin C was found to be significantly associated with mortality, regardless of kidney function, among elderly, patients admitted to intensive care unit (ICU), human immunodeficiency virus (HIV)-infected persons, and patients with cardiac diseases." (PMID 40707908, 2025). "Growth differentiation factor-15 (GDF-15), Cystatin C and C-reactive protein (CRP) have been discussed as biomarkers for prediction of cardiac diseases." (PMID 29771963, 2018). "Also in cluster 4 were Cystatin-3 (CST3) and Vitronectin (VTN), proteolysis inhibitors which have been described as robust biomarkers of heart disease." (PMID 34741130, 2022).
metabolic disease (8 papers, 2016 to 2025). A congenital disorder (due to inherited enzyme abnormality) or acquired (due to failure of a metabolically important organ) disorder resulting from an abnormal metabolic process. "Overall, the increased levels of UACR and the urinary cystatin C/creatinine ratio indicate dysfunctions in the glomerulus and proximal tubule, and confirm the establishment of the metabolic disorder-induced CKD model." (PMID 27097221, 2016). "In contrast, the impact of declining health on cystatin C is independent of muscle mass, though may be related to accrual of metabolic disease, resulting in a more linear decrease in eGFRcys." (PMID 40235956, 2025). "However, neither hs-CRP nor ghrelin, leptin or cystatin C correlated with metabolic disease remission after surgery in either group." (PMID 33208757, 2020). "The results reconfirmed the correlation with MetS and suggested that non-GFR determinants of cystatin C might participate in the process of metabolic disorder." (PMID 31317040, 2019).
infectious disease (2 papers, 2017 to 2023). A disorder directly resulting from the presence and activity of a microbial, viral, or parasitic agent in humans. "Cystatin C (Cys C) not only regulates the body's immune defenses but also contributes to tissue degradation and destruction by causing an imbalance between protease and antiprotease in infectious diseases." (PMID 37091891, 2023).
neuromuscular disease (2 papers, 2021 to 2022). "This study was designed to evaluate the precision, accuracy, and bias of two creatinine-, one cystatin C-based and one combined equation to estimate glomerular filtration rate (eGFR) in patients with primary neuromuscular diseases." (PMID 34351595, 2022). "Cystatin C-based estimations of kidney function performed better than creatinine-based ones in patients with primary neuromuscular disease, but most importantly, all evaluated equations overestimated kidney function, especially in patients with reduced kidney function." (PMID 34351595, 2022). "In conclusion, our findings indicate that a cystatin C-based estimation of kidney function may be more accurate in patients with primary neuromuscular disease and low muscle mass." (PMID 34351595, 2022).
psychiatric disease (2 papers, 2017 to 2025). "Meanwhile, cystatin C has been noted in some psychiatric disorders, and elevated serum cystatin C levels suggest potential diagnostic capabilities in these diseases." (PMID 40256164, 2025).
Retinopathy (2 papers, 2015 to 2024). "It is possible that cystatin C could also be a better predictor for DR compared to eGFRcr and albuminuria, related to shared pathogenic pathways between retinopathy and cystatin C." (PMID 26576434, 2015). "Among these groups, the level of uric acid (UA), estimated glomerular filtration rate (eGFR), Creatinine (Cr) and Serum cystatin C (CysC) was higher in DR than DM, indicating poor kidney function in diabetic patients with retinopathy." (PMID 38755602, 2024).
diseases of the brain (1 paper, 2014). "It has also been reported that cystatin C is present in high concentration in CNS and is suggested to play an important role in diseases of the brain." (PMID 25170426, 2014).
peripheral neuropathy (1 paper, 2019). A disorder affecting the peripheral nervous system. "Previous studies have proved that cystatin C (CysC) is an important predictor of both peripheral neuropathy and cardiovascular events." (PMID 31011584, 2019).
CST3 also shares sentences with these, for which no sentence is quoted: acute myocardial infarction (11 papers); diabetic retinopathy (9); cholestasis (5); chronic lung disease (5); Lewy body dementia (5); respiratory disease (5); Hypoalbuminemia (4); multiple system atrophy (4); systemic lupus erythematosus (4); chronic periodontitis (3); dyslipidaemia (3); gastrointestinal stromal tumor (3); Gestational Diabetes Mellitus (3); hypertriglyceridemia (3); osteoarthritis (3); peripheral vascular disease (3); Thrombocytopenia (3); unstable angina (3); acute-on-chronic liver failure (2); aortic aneurysm (2); autosomal dominant polycystic kidney disease (2); benign tumors (2); cholangiocarcinoma (2); coronary artery calcification (2); cystinosis (2); dialysis (2); diastolic heart failure (2); endotoxemia (2); essential hypertension (2); familial British dementia (2).
A further 153 diseases each share a sentence with CST3 in 2 papers or fewer.